IL6 (interleukin 6)
Diseases named in the same sentence as IL6 in open-access papers (continued):
Sharing a sentence is not in itself a finding about the gene and the disease.
tumor (continued). "In an inflammatory state, estrogen promotes colon cancer, and further studies have shown that estrogen also promotes tumor growth in already tumor-bearing mice, which may be due to estrogen exacerbating inflammation through IL-6." (PMID 40406485, 2025). "Moreover, hypoxic conditions in the tumor microenvironment upregulate IL-6 secretion by CAFs via HIF-1α-dependent mechanisms, promoting CRC cell proliferation and survival." (PMID 40718440, 2025). "Additionally, IL-6 expression was noted in stromal immune cells, including macrophages, within the tumor microenvironment." (PMID 41007818, 2025). "We explored whether disrupting IL-6 signaling in the TME could increase monocyte migration from the bone marrow into the tumor." (PMID 39653766, 2025). "Furthermore, FABP5 regulates the expression of VEGF through PPARγ and enhances the expression of other angiogenic factors, including EGF and IL‐6, thereby promoting tumor angiogenesis." (PMID 40178066, 2025). "These AGEs activate inflammatory signaling cascades such as the NF-κB and STAT3 pathways, resulting in increased production of pro-inflammatory cytokines (e.g., interleukin-6 and tumor necrosis factor-alpha) that induce DNA damage, inhibit apoptosis, and promote tumor progression." (PMID 41479778, 2025). "Notably, TNF-alpha signaling via NF-κB and IL6/JAK/STAT3 signaling have been widely characterized to foster an inflammatory tumor microenvironment that favors metastasis." (PMID 39489818, 2025). "Another clinically relevant inflammatory cytokine present in the PCa tumor environment is IL-6." (PMID 41374981, 2025). "IKK inhibitors and proteasome inhibitors can suppress the nuclear translocation of NF-κB either directly or indirectly, leading to the downregulation of inflammatory cytokines (e.g., TNF-α, IL-6) and anti-apoptotic genes, thereby contributing to tumor microenvironment modulation." (PMID 41169368, 2025). "IL-6 also modulates the immune milieu; it recruits and polarizes myeloid cells that suppress T cell activity, thereby creating an immunosuppressive environment that facilitates tumor growth." (PMID 41007766, 2025). "Notably, specific expression profiles emerged for IL6, sPD-L1, sTIM3, sCD27 and sSIGLEC5 across the different neoplasms." (PMID 40038821, 2025). "We hypothesized that the Toe-Macs in NSCLC are pathogenic, in part due to enhanced expression of the key tumor-promoting factors NLRP3, IL-1β, TGF-β1, CCL2, IL-6, and PD-L1 (encoded by CD274)." (PMID 40794443, 2025). "Finally, tumor-promoting inflammation was also identified as a relevant enabling mechanism, specifically, the presence of proinflammatory cytokines such as IL-6 (SMD = −1.07, 95% CI = −1.86 to −0.28, p = 0.008) or TNF-α." (PMID 40805130, 2025). "Urinary and serum IL-10 levels are biomarkers for tumor occurrence, while the IL-6 to IL-10 ratio may be a potent predictor of NMIBC recurrence." (PMID 40227644, 2025). "Notably, our combination therapy effectively counteracts the immunosuppressive TME by reducing M-MDSC and Treg infiltration, which are known to promote tumor progression through secreting inhibitory cytokines (IL-6, IL-10, and TGF-β)." (PMID 40625660, 2025). "Interleukin-6 (IL-6) is thought to play a central role in its pathogenesis, and the syndrome may resolve completely after tumor resection." (PMID 41301732, 2025). "In addition, IL-6 directly promotes the proliferation, survival, and invasion of tumor cells by activating STAT3 signaling." (PMID 41376630, 2025). "For example, combining IL6 with other protein markers like TNFR2 could strongly indicate aggressive tumor activity in OC." (PMID 40427188, 2025). "Given the pivotal role of the IL6/JAK2/STAT3 axis in promoting tumor progression and shaping an immunosuppressive microenvironment, we performed immunohistochemical analysis of phosphorylated JAK2 and STAT3 in tumor tissues from the mouse model to validate pathway activation." (PMID 40384867, 2025).
tumor (continued). "Additionally, studies by Culig and Puhr have shown that silencing IL-6 using siRNA prevents tumor recurrence following radiotherapy in prostate cancer and increases tumor cells’ sensitivity to radiation." (PMID 40895459, 2025). "Given the pivotal role of the IL-6/STAT3 axis in promoting tumor growth, survival, and inflammatory signaling, this robust inhibition indicates that KAE exerts potent anti-inflammatory and anticancer activity, nearly matching the efficacy of the standard chemotherapeutic." (PMID 41515404, 2025). "Adipocytes, a prominent component of the adipose-enriched tumor microenvironment, contribute to cancer progression through the secretion of cytokines (e.g., leptin, interleukin-6), extracellular vesicles, providing lipids and the extracellular matrix remodeling." (PMID 40616161, 2025). "Therefore, integrating IL‐6 and GDF‐15 inhibitors into therapeutic regimens warrants further investigation to disrupt the deleterious cycle of inflammation, muscle loss and tumour progression." (PMID 41380167, 2025). "For instance, the proangiogenic factors released by cancer cells to promote angiogenesis and tumor development may be enriched by IL-6 produced by MSCs; addressing this relationship may result in new preventative and therapeutic approaches." (PMID 40534879, 2025). "SYD has been found to reduce key inflammatory markers such as IL‐1, IL‐6, and TNF‐α, resulting in decreased tumor‐associated macrophage (TAM) infiltration and NF‐κB activation, thereby inhibiting Snail‐induced epithelial–mesenchymal transition (EMT) and subsequently CRC progression." (PMID 40119640, 2025). "Furthermore, the hyperactivation of the IL-6/JAK/STAT3 signaling pathway can suppress antitumor immune responses in the tumor microenvironment, allowing cancer to persist." (PMID 40558287, 2025). "Moreover, cytokines secreted by TAM M2, including TNF-α, ICAM-1, and IL-6, further contribute to tumor growth and invasion." (PMID 40299539, 2025). "F. nucleatum can induce EMT and tumor cell stemness via the IL-6/STAT3 signaling pathway." (PMID 41597595, 2025). "Additionally, when co-cultured with tumor cells, BBζ-Neo exhibited higher levels of IFNγ, IL-1β, IL-6, MCP-1, TNF-α and IL-8 compared to BBζ." (PMID 40025022, 2025). "To ascertain whether tumor cells promote the secretion of IL-6 by activating UPR, we employed the ER stress inhibitor 4-PBA to inhibit the UPR." (PMID 41254082, 2025). "A lesser role for IL-6 has been evidenced in which it displays an anti-tumor effect." (PMID 41376623, 2025). "Collectively, these results indicate that elevated IL-6 levels within the NSCLC tumor microenvironment promote the ubiquitination and subsequent degradation of NKp30 in NK cells by activating the STAT3-UBE2S signaling axis, thereby impairing NK cell cytotoxic function." (PMID 41254082, 2025). "Following LDHC knockdown, we observed an increase in the secretion of tumor-derived pro-inflammatory cytokines (IFN-γ, GM-CSF, MCP-1, CXCL1), a decrease in the soluble levels of tumor-derived immunosuppressive factors (IL-6, Gal-9) and reduced tumor cell surface PD-L1 expression." (PMID 40108668, 2025). "In addition, miR-155 can inhibit IL-6 to play a variety of carcinogenic effects in the tumor microenvironment by targeting cytokine signaling." (PMID 41450733, 2025). "Importantly, preclinical studies have demonstrated that blockade of the IL-6/STAT3 axis restores anti-tumor immune responses by relieving T cell suppression and enhancing adaptive immunity." (PMID 40704145, 2025). "In HER2 + BC, senescent cells exclusively secreted IL6, driving tumor growth." (PMID 40781676, 2025).
tumor (continued). "Notably, targeted inhibition of interleukin-6 receptor (IL-6R), which is highly expressed in ALDHhigh ECSCs, leads to a marked reduction in tumor cell growth, highlighting the critical role of IL-6 signaling in CSC maintenance." (PMID 41373619, 2025). "In addition, Gal-3 promotes the release of many inflammatory cytokines, such as interleukin (IL)-6 and IL-8, by stromal cells, which accelerates tumor progression through deterioration of the tumor microenvironment." (PMID 40600063, 2025). "The interleukin-6 (IL-6) cytokine family includes IL-6, IL-11, IL-30, IL-31, and non-IL molecules, primarily secreted by lymphocytes, monocytes/macrophages, adipocytes, tumor cells, and endothelial cells." (PMID 41035635, 2025). "Other research suggested that IL‐6 may serve as a critical mediator connecting systemic inflammation, muscle wasting, and tumour progression." (PMID 41380167, 2025). "IL-6 and TNFα, key mediators in inflammatory processes, are central targets in immunotherapy due to their roles in tumor progression and immune modulation and their activity influencing nearly all biological processes, depending on the production levels and surrounding conditions." (PMID 40004468, 2025). "Similarly, IL6 is a well-known proinflammatory cytokine that can enhance tumor progression by driving persistent inflammation." (PMID 40650134, 2025). "Preclinical and clinical studies have indicated that blocking IL-6, alongside PD-1/PD-L1 inhibitors, may offer a more effective treatment by mitigating the inflammatory environment that fuels tumour growth." (PMID 40544399, 2025). "By disrupting the regulatory effects of IL-10 and IL-6, it may be possible to enhance anti-tumor immunity and improve the efficacy of existing cancer therapies." (PMID 41583453, 2025). "For instance, cytokines in the tumor microenvironment (e.g., IL‐6) may activate STAT3 through bypass pathways, thereby compromising the efficacy of SRC‐1 inhibitors." (PMID 40985319, 2025). "Importantly, we also measured IL‐6 and IL‐8, key inflammatory mediators in the tumor microenvironment." (PMID 40249196, 2025). "Additionally, IL6 has been shown to create a “cold” tumor microenvironment in OC, making it less responsive to immunotherapy and leading to worse clinical outcomes." (PMID 40427188, 2025). "Furthermore, in IL-6-deficient mice, HT increased ICAM-1 expression on tumor vessels and induce CD8+ T-cell infiltration into the tumor." (PMID 40092992, 2025). "Additionally, CAFs increase IL-6 and IL-8 secretion in tumor cells, promoting invasion and angiogenesis." (PMID 40647432, 2025). "This cytokine can promote tumor growth and progression under certain conditions by stimulating the production of other inflammatory cytokines and chemokines, including interleukin-17 (IL-17), IL-6, and IL-27." (PMID 41254398, 2025). "CRS results from the robust activation of CAR T cells upon encounter with tumor cells, leading to a surge in pro-inflammatory cytokines, including interleukin 6 (IL-6), interferon gamma (IFNγ), interleukin 1 (IL-1), and tumor necrosis factor alpha (TNF-α), that drive systemic inflammation." (PMID 41323217, 2025). "In addition, CAFs secrete substantial amounts of growth factors, proinflammatory cytokines, and chemokines, particularly TGF-β, IL-6, and CC-chemokine ligand 2, which recruit immunosuppressive cells into the tumor stroma and lead to immune escape 20-22." (PMID 39897553, 2025). "In addition, we found that the plasma cytokine profile in the tEVs group manifested pro-tumor characteristics, such as increased IL-6 and decreased IL-12p40, IL-12p70." (PMID 41050665, 2025). "Additionally, anti‐angiogenic therapy has been found to normalize disorganized tumor blood vessels and reduce the recruitment of immune‐inhibitory factors such as IL‐6, IL‐10, and indoleamine 2,3‐dioxygenase (IDO), improving the efficacy of immunotherapy." (PMID 40105370, 2025).
tumor (continued). "Additionally, DCs in the OC-TME secrete IL6 in a paracrine manner, helping maintain their immature, immunosuppressive state and further hindering anti-tumor immune responses." (PMID 40427188, 2025). "By inhibiting pro-inflammatory cytokines like tumor necrosis factor (TNF)-α and IL-6, these compounds may reduce the chronic inflammation that fuels tumor growth." (PMID 40507159, 2025). "Serum IL-6 is a pro-inflammatory cytokine involved in immune responses and tumor progression." (PMID 41007708, 2025). "Furthermore, tumor-derived exosomal heat shock protein 72 enhances MDSC expansion by activating STAT3 via TLR2/MyD88-dependent autocrine IL-6 production, reinforcing an immunosuppressive tumor microenvironment TME." (PMID 40861469, 2025). "Furthermore, treatment with an IL-6 neutralizing antibody (α-IL-6) reduced PD-1 abundance in tumor-infiltrating CD8+ T cells." (PMID 40238877, 2025). "Furthermore, in HCC, M2 macrophages have been shown to contribute to tumor progression via the IL-6/STAT3 signaling pathway." (PMID 39652104, 2025). "We speculate that tumor-derived cytokines such as interleukin-6 and vascular endothelial growth factor might impair earlobe microcirculation; however, coincidental coexistence cannot be excluded." (PMID 40734893, 2025). "Plasma IL‐6 levels were higher in K and KL tumours compared to controls in both sexes." (PMID 40702652, 2025). "PI3K/Akt in TAMs integrates CSF1R/IGF-1R/TLR inputs to drive mTORC1-linked biosynthesis and secretion of IL-6, TGF-β, and pro-angiogenic factors, which in turn activate survival/DNA-repair pathways in adjacent tumor cells and generate leaky neovasculature that impairs drug delivery." (PMID 41002423, 2025). "However, IL-6 is also known to correlate with the malignancy potential of the tumor itself, such as in patients with advanced stage HCC or high AFP, and has been reported to contribute to shorter OS regardless of treatment." (PMID 39652104, 2025). "Moreover, IL-1 beta promotes tumor cell proliferation, survival, and migration, while IL-6 facilitates tumor immune evasion." (PMID 40805215, 2025). "CAFs-derived IL-6 may promote tumor proliferation by regulating osteopontin expression in a STAT3-dependent manner." (PMID 40136652, 2025). "In cancer development, IL-6 promotes tumor growth, metastasis, and immune evasion by activating oncogenic signalling pathways, enhancing cancer cell proliferation, survival, and angiogenesis and suppressing anti-tumor immune responses." (PMID 40650089, 2025). "Growing validations indicated that the KRAS mutations may mainly produce an immunosuppressive TME by facilitating the development of immunomodulatory markers in tumor cells, including interleukin-6, transforming growth factor, and interleukin-10." (PMID 40075634, 2025). "The IL-6/STAT3 pathway plays a role in promoting tumor growth and metastasis in various cancers, and thus its inhibition may slow the progression of HCC." (PMID 40919140, 2025). "Moreover, pro-inflammatory cytokines IL-6 and IL-8 were elevated, indicating their involvement in the initial stages of tumor clustering and suggesting them as potential therapeutic targets in metastasis." (PMID 41516217, 2025). "Similarly, miR-127 enhances the expression of pro-inflammatory cytokines like IL-6 and IL-1β, suggesting its potential role in promoting an M1 phenotype, which is geared towards fighting infections and tumor cells." (PMID 40821768, 2025). "Neutrophils and key signaling pathways, such as NF-κB and cytokines like TNF-α and IL-6, enhance tumor progression, which may explain the observed increase in NLR in more aggressive tumors." (PMID 40141182, 2025). "TNF-R2 may also collaborate with TNF-α and other proinflammatory cytokines, such as IL-6, to enhance VS tumor growth, as its expression can be jointly driven by TNF-α and IL-6." (PMID 39923035, 2025).
tumor (continued). "Importantly, these findings align with scRNA-seq data revealing enrichment of cytokine-cytokine receptor pathways in tumor-infiltrating NK cells, suggesting IL-6 as a key modulator of NK cell dysfunction in the tumor microenvironment." (PMID 41254082, 2025). "Furthermore, SASP factors (IL-6, IL-8, MMP3) secreted from these senescent HUVECs act on surrounding cells such as tumor-associated macrophages (TAMs) and cancer-associated fibroblasts (CAFs), thereby facilitating tumorigenesis." (PMID 41008624, 2025). "Furthermore, several other marker genes that are known to support tumor growth and creating an immune suppressive environment like IL6, IL10, C1QA, interleukin‐1 receptor antagonist (IL1RN), and KYNU were highly expressed in our Tri culture condition." (PMID 40056038, 2025). "Such stromal rearrangements might form a barrier physically excluding T cells from penetrating into the tumor core, despite activated inflammatory IL-6 signaling and CXCR2 chemokine gradient." (PMID 40809430, 2025). "IL-6 and TNF-α are central activators of NF-κB, driving angiogenesis, epithelial–mesenchymal transition, and resistance to apoptosis, while IL-1β has been implicated in promoting immunosuppression and metastatic spread within the tumor microenvironment." (PMID 41020906, 2025). "Results of the in vivo study included suppression of EAC tumor burden, enhanced apoptosis (Annexin V/PI), reduced IL-6 and TNF-α cytokines, and preserved liver/kidney function, confirming synergistic antitumor and immunomodulatory effects with a favorable biosafety profile." (PMID 40943339, 2025). "Studies show that adding IL-6 to tumor/NK cell cultures lowers NK-mediated IFN-γ secretion." (PMID 41008790, 2025). "CHI3L1 can directly stimulate tumor cells to produce proinflammatory cytokines (IL-6, IL-8, and transforming growth factor-β) and activate the transforming growth factor-β signaling pathway through binding to its receptor, resulting in proinflammatory cytokine production and immune cell recruitment." (PMID 40260255, 2025). "In lung cancer, particularly in Non-Small Cell Lung Cancer (NSCLC), TAMs in the TME play an important role because they are associated with the production of various pro-inflammatory cytokines and chemokines (IL-1β, IL-6, IL-8, IL-12, and IL-18), promoting tumor growth and metastasis." (PMID 41560727, 2025). "On the other hand, IL-6 promotes tumor growth, angiogenesis and immune escape by regulating immune balance and activating multiple signaling pathways, and becomes a potential target for anti-tumor therapy." (PMID 39897552, 2025). "Similarly, Fusobacterium nucleatum in CRC patients activates Wnt/β-catenin signaling, increasing inflammatory cytokines (e.g., IL-6, IL-8) and fostering tumor proliferation." (PMID 39996827, 2025). "The association between baseline CRP elevation and inferior OS (HR = 3.337; p=0.044) underscores systemic inflammation’s role in ES-SCLC progression-a finding consistent with mechanisms linking interleukin-6-driven inflammation to immunosuppression and tumor aggressiveness." (PMID 41267986, 2025). "Besides, IL-6 contributes to tumorigenesis by promoting growth, metastasis, and therapy resistance through modulation of the tumor microenvironment." (PMID 40770768, 2025). "At the same time, increased expression of IL6 and IL8 may in some cases support processes associated with tumor progression, such as angiogenesis or cell migration." (PMID 40725171, 2025). "Recent pre-clinical studies that control food intake and tumor burden suggest that the effects of IL-6 on body weight and tissue mass may be indirect." (PMID 41278737, 2025). "The mechanism by which Clostridium butyricum influences macrophages is associated with its binding to the GRP78 receptor on tumor cell surfaces via the surface protein secD, thereby blocking the PI3K-Akt-NF-κB signaling axis and reducing IL-6 secretion by tumor cells." (PMID 41048488, 2025).